MIR3152 (microRNA 3152)
Synonyms: hsa-mir-3152
Gene: MicroRNA gene on chromosome 9 (18,573,306 to 18,573,379, forward strand). Ensembl gene ENSG00000264638.
Homologues: Orthologues: chimpanzee MIR3152 (100% identical).